RPL7P52 (ribosomal protein L7 pseudogene 52)
Synonyms: RPL7_21_1751
Gene: Processed pseudogene on chromosome 22 (40,106,325 to 40,107,066, reverse strand). Ensembl gene ENSG00000228599.
Diseases named in the same sentence as RPL7P52 in open-access papers:
RPL7P52 is named in the same sentence as 1 disease in open-access papers, as found by Europe PMC text mining. Sharing a sentence is not in itself a finding about the gene and the disease. The quoted sentences say what the papers report.
cancer (1 paper, 2021). A tumor composed of atypical neoplastic, often pleomorphic cells that invade other tissues. "Of these genes, six lncRNA (AL360091.3, AL360175.1, AC025254.1, AC093801.1, AC092354.1 and AC016722.1); four pseudogenes (RBM22P2, AC073324.1, OR1X1P, RPL7P52 and MTND5P25) and coding SLC36A2 and SDS and have not previously been shown to be transcripts in cancer." (PMID 34026616, 2021).